AXL (AXL receptor tyrosine kinase)
Diseases named in the same sentence as AXL in open-access papers (continued):
Sharing a sentence is not in itself a finding about the gene and the disease.
tumor (continued). "It was demonstrated, for the first time, that the abundance of EGFR, INSR, VGFR3 and AXL, is lower in tumours relative to livers from healthy individuals whilst the opposite is true for IGF1R." (PMID 36890818, 2023). "The combination of AXL inhibitors increased sensitivity to ostatinib treatment compared with ostatinib monotherapy, both in primary and resistant cases, thereby reducing tumor size and slowing tumor growth." (PMID 37265798, 2023). "To validate the mechanism underlying, we examined the related protein level of p-TRKB, p-c-Met, p-AXL, Cyclin D1and NF-κB in tumor tissues of three mice." (PMID 37945598, 2023). "AXL expression on specialized phagocytes (macrophages and dendritic cells) in various tumor settings is important for homeostasis under physiological conditions." (PMID 37265798, 2023). "Roles for Gas6/AXL signaling in cancer development and progression, and shaping of the tumor microenvironment are gradually being revealed." (PMID 37265798, 2023). "In fact, if combining AXL inhibition and dexamethasone enhances anti-tumor immune responses this would be an unexpected result." (PMID 37035141, 2023). "It’s well documented that AXL functions in triggering an immunosuppressive tumor microenvironment resulting in immune evasion." (PMID 36823234, 2023). "Gas6/AXL signaling promotes immunosuppression and generates a pro-tumor microenvironment by altering and regulating the secretion of cytokines associated with immune cell function and movement." (PMID 37265798, 2023). "The AXL signaling is related to tumor cell self-renewal, invasion, metastasis, EMT, angiogenesis, and drug resistance." (PMID 36982236, 2023). "The GAS6/AXL signalling pathway has been shown to promote tumour cell proliferation and survival as well as EMT and immune evasion." (PMID 37313656, 2023). "Anti-AXL CAR T-cells demonstrate significant anti-tumor activity in TNBC models and have the potential to overcome the immunosuppressive microenvironment by inhibiting TAM cytokine secretion." (PMID 38201551, 2023). "BPI-9016M is a novel small-molecule TKI targeting both c-MET and AXL developed by Betta Pharmaceuticals Co., Ltd, Hangzhou, China., which can suppress tumor cell growth, migration and invasion of lung adenocarcinoma." (PMID 37041472, 2023). "Three of thirty-nine proteins (PCDHA4, AXL, and NAMPT) correlate with RMS and RMS-associated tumor behavior." (PMID 36918772, 2023). "BPI-9016M is a novel small-molecule TKI that targets both c-MET and AXL, which inhibits tumor cell growth, migration and invasion in NSCLC." (PMID 37041472, 2023). "The loss-of-function mutations in this tumor-suppressor gene result in the accumulation of HIF1α/2α, eventually leading to overexpression of VEGF/PDGF, AXL, and MET, among others." (PMID 37400554, 2023). "In general, AXL is expressed on tumor cells, but recent reports detected AXL on bone marrow-derived cells (BMDC), dendritic cells (DC), giant phagocytosis cells, mononuclear cells, natural killers (NKs) and platelets." (PMID 37265798, 2023). "Out of these 5 hub genes, only CCND1 have high median mRNA expression in normal patients than primary tumor whereas AXL, CDKN2A, TERT, and EZH2 have high expression in the primary tumor." (PMID 36715825, 2023). "In particular, it would be intriguing to further evaluate the treatment outcome in patients with AXL‐positive tumors as only 1 patient showed tumor AXL positivity in this study." (PMID 36621830, 2023). "The aptamer GL21.T fulfils these criteria, preliminary data show it binds AXL with high affinity, blocks AXL-dependent signal transduction pathway, and inhibits tumor migration and invasion." (PMID 37328828, 2023). "Some cancer models further revealed that AXL expression is related to tumor cell motility, metastasis, and invasion." (PMID 37265798, 2023). "Histological analysis of liver tissues demonstrates that inhibition of AXL expression by genetic knockdown also decreases tumor growth in the orthotopic setting as well." (PMID 36980768, 2023).
tumor (continued). "Genetic deletion of AXL resulted in sensitization of tumor cells to radiation and checkpoint immunotherapy." (PMID 36982920, 2023). "A recent mouse study demonstrated that AXL inhibitors impact the immune status and tumor growth in lung cancer." (PMID 37265798, 2023). "When TYRO3 expression was higher than AXL, tumor cells proliferated and, on the other hand, when AXL expression levels exceeded those of TYRO3, the cancer cells remained largely quiescent." (PMID 38203403, 2023). "In transgenic mouse models, AXL gene deletion increases T-cell infiltration in the tumor microenvironment by up to 20 times, while making tumor cells 50 times more sensitive to radiotherapy and immune checkpoint therapy." (PMID 37265798, 2023). "The tumour growth in CAM was greatly suppressed when treated with the AXL and ATR combination treatment compared to either single agent." (PMID 37349576, 2023). "We show that the metformin-induced suppression of tumor growth in vivo is highly dependent on AXL expression in a tumor xenograft mouse model of EAC." (PMID 35936716, 2022). "STS PDX tissue microarrays containing tumor tissue from all available models (n = 45) were evaluated for AXL immunopositivity." (PMID 35886842, 2022). "In recent years, as a member of the TAM family, AXL has received considerable attention in studies of tumour immunity." (PMID 36203174, 2022). "As such, a more detailed understanding of the functions of AXL in various tumor cell types, including both in cancer and different stromal cells, is needed." (PMID 35158733, 2022). "This angiogenesis then leads to tumor and metastatic growth and AXL has been shown to play a role in this process." (PMID 35158733, 2022). "A study in cell lines evaluated the use of cabozantinib and osimertinib in osimertinib-resistant NSCLC with AXL upregulation, observing a significant tumor suppression." (PMID 35454838, 2022). "In this review, we aim to summarize the current knowledge regarding the regulation and function of AXL in cancer and discuss mechanisms involving AXL in the escape from anti-tumor immunity." (PMID 35572601, 2022). "To explore how MWA enhances the accumulation and killing activity of AXL-CAR T cells in NSCLC PDX tumours, we analysed several key limiting factors in the TME." (PMID 36261437, 2022). "Tissue microarrays containing archived tumor tissue from all available models (n = 45) were stained and evaluated for AXL expression." (PMID 35886842, 2022). "The calculated tumour volume grew slowly in the AXL-CAR T group, but increased dramatically compared to the baseline (50 mm3) in the mock (phosphate buffered saline, PBS) and CD19-CAR T groups." (PMID 36261437, 2022). "MWA enhances the activation, infiltration, persistence and tumour suppressive properties of AXL-CAR T cells in AXL-positive NSCLC patient-derived xenograft tumours via TME remodelling." (PMID 36261437, 2022). "Here, we review the current literature on the prominent role of AXL in regulating cancer progression, with particular attention to its effects on anti-tumor immune response and resistance to ICI." (PMID 35572601, 2022). "AXL is a receptor tyrosine kinase involved in tumor progression, and the overexpression of AXL on tumor cells is correlated with poor prognosis in several cancers including TNBC." (PMID 35795050, 2022). "AXL signaling operates as a critical pathway mediating tumor cell survival, expansion, migration, and invasion suggesting the potential of AXL as a suitable cancer treatment target antigen." (PMID 36483567, 2022). "Immunoblotting of transplanted tumor tissues from BALB/C-nude mice indicated that DCC-2036 significantly inhibited p-AXL, AXL, and KLF5." (PMID 36042208, 2022). "AXL activation in cancer cells and various stromal cells also results in tumor microenvironment deregulation, leading to modulation of angiogenesis, fibrosis, immune response and hypoxia." (PMID 35158733, 2022).
tumor (continued). "IGF1R and AXL activate Akt signaling and increase mitochondrial performance, proliferation, and resistance to apoptosis in tumor cells." (PMID 35159011, 2022). "Upon binding to its ligand GAS6, AXL regulates cell signaling cascades and cellular communication between various components of the tumor microenvironment, including cancer cells, endothelial cells, and immune cells." (PMID 35572601, 2022). "The receptor tyrosine kinase AXL is required at many steps of the metastatic cascade and contributes to tumor microenvironment deregulation." (PMID 35158733, 2022). "AXL is a member of the receptor tyrosine kinase family, which is involved in tumor growth, invasion and metastasis." (PMID 36482474, 2022). "We demonstrated that AXL expression is highly predictive of the suppressive effect of metformin on tumor growth." (PMID 35936716, 2022). "FACS analysis with tumor cells over-expressing AXL and the use of an AXL knock-out cell line allowed us to identify Pronectin candidates with exquisite specificity for AXL receptor." (PMID 36551940, 2022). "In this study, we examined the effect of AXL inhibitors on immune activation and tumor growth in TC1 and C3PQ mouse tumor models, in the context of clinical immunotherapy/chemotherapy and maintenance treatment, using an aPD-1 with/without pemetrexed." (PMID 35356198, 2022). "Overexpression of AXL contributes to tumor progression by facilitating tumor growth, invasion/metastasis, drug resistance and epithelial–mesenchymal transformation (EMT)." (PMID 35805163, 2022). "The receptor tyrosine kinase AXL is emerging as a key player in tumor progression and metastasis and its expression correlates with poor survival in a plethora of cancers." (PMID 35158733, 2022). "Both the MET and AXL signaling pathway play crucial roles in HCC tumor progression, invasion, and metastasis, with their overexpression acting as predictors of poor prognosis in patients with HCC." (PMID 35062934, 2022). "In this model, AXL expression is weak in macrophages and high in tumor and DCs, whereas MERTK and TYRO3 expression is marginal in carcinoma cells and restricted to macrophages and DCs." (PMID 35572601, 2022). "Significantly, intravenous injection of AXL‐CAR‐T cells into the mouse model of TNBC MDA‐MB‐231 xenografts inhibited tumour development." (PMID 35762299, 2022). "The increase in CD8+ central memory T cells was significant only in the C3PQ tumor model with upfront inhibition of AXL." (PMID 35356198, 2022). "Then, neutrophil-derived Gas6 induces AXL Receptor Tyrosine Kinase (AXL) on metastatic tumor cells and finally contributes to metastatic growth in liver." (PMID 36091114, 2022). "When analyzing tumor cells, AXL staining was detected predominantly in the cell membrane and cytoplasm." (PMID 35332208, 2022). "Collectively, these phenomena enhanced the accumulation and function of AXL-CAR T cells in NSCLC PDX tumour model." (PMID 36261437, 2022). "In this regard, we evaluated the expression of SOX2 in blood mononuclear cells expressing tumor markers such as AXL, EGF, CD87, CD90, or CD276." (PMID 36142766, 2022). "We showed that inhibition of WNK1 reduces tumor volume and dispersion of metastatic cells in a mouse xenograft model of metastatic breast cancer, in part, via a network involving Slug and AXL." (PMID 35813203, 2022). "Once EnaV binds to AXL expressed on the cell membrane of AXL-positive tumor cells, the complex is internalized and cleaved by lysosomal proteases, releasing free MMAE." (PMID 35886842, 2022). "Given that patients with tumor AXL- and stromal Gas6-positive tumors had significantly lower five-year disease-free survival rates than the double negative group, it was concluded that Gas6 is involved in poor clinical outcomes." (PMID 35053080, 2022). "Regarding our study, AXL, along with its downstream signaling pathway, shares a pathogenesis of tumour oncogenesis similar to that of other tyrosine kinase families." (PMID 36203174, 2022).
tumor (continued). "AXL- or CD19-CAR T cells were used to treat mice bearing established subcutaneous tumour xenografts formed by A549 or HCC827-ER3 cells." (PMID 36261437, 2022). "This review highlights novel discoveries about AXL functions in different tumor compartments and discusses potential therapeutic interventions through AXL inhibition." (PMID 35158733, 2022). "IGF1 and GAS6 act as paracrine-reciprocal signals for activating the receptor tyrosine kinases IGF1R and AXL (“anexelenko”, which means “uncontrolled” in Greek), respectively, in tumor cells." (PMID 35159011, 2022). "These new findings regarding AXL signaling, and biology further confirm its role in cancer cell dissemination through the reprogramming of cells to be able to leave the primary tumor and enter a distant organ by increasing cell motility." (PMID 35158733, 2022). "CT053PTSA is a potent inhibitor of MET, AXL, VEGFR-2, FMS-like tyrosine kinase 3 (FLT3) and MERTK, all of which have been implicated in tumor pathogenesis." (PMID 36341335, 2022). "Correspondingly, the measured average tumour weights in the AXL-CAR T group (A549 0.28 g, HCC827-ER3 0.40 g), were significantly lower than those in the CD19-CAR T (A549 0.68 g, HCC827-ER3 0.82 g) and mock (A549 0.72 g, HCC827-ER3 1.00 g) groups." (PMID 36261437, 2022). "AXL54-x-CD3 is designed as a bi-specific protein that will link AXL-expressing tumor cells and T-cells via the CD3 receptor." (PMID 36551940, 2022). "In vitro and in vivo studies have been undertaken with ADCT-601, an antibody drug conjugate targeting AXL, which has preliminarily shown significant tumor response rates in high AXL-expressing ACC mouse models." (PMID 36428790, 2022). "Previous work on human NSCLC carcinoma cells from the IGR-Heu model, also provided an exciting insight into AXL-mediated molecular mechanisms of tumor immune evasion." (PMID 35572601, 2022). "Several genes were found at lower expression levels in tumor cases, such as AXL, BAHC2, CFLAR, and DNMT1 while others were overexpressed such as BNIP3, DIABLO, FADD, and IDH1." (PMID 35911707, 2022). "AXL has been noted to influence clinically meaningful end points including metastatic recurrence and survival in the vast majority of tumor types." (PMID 36551940, 2022). "An ADC comprised of an AXL antibody conjugated to an antimitotic drug blocked tumor growth in vitro and in vivo in treatment-naïve and targeted therapy-resistant CM, and these effects were enhanced upon the addition of BRAFi and MEKi." (PMID 35513054, 2022). "The AXL is expressed in tumor cells and plays an essential role in cancer resistance to chemotherapy and immunotherapy." (PMID 35356198, 2022). "Combination or AXL-CAR T treatment induced downregulation of CD206+ expression from CD68+ macrophages in tumours, which is consistent with decreased M2 polarization." (PMID 36261437, 2022). "We also performed flow cytometry-based immune profiling of myeloid cells and lymphoid cells at different points in the treatment schedule, to investigate the immune activation and anti-tumor effects of the AXL inhibitor." (PMID 35356198, 2022). "AXL is also known to contribute to cancer progression, metastasis and therapy resistance by reprogramming the tumor microenvironment to be more favorable for cancer progression." (PMID 35158733, 2022). "In the current study, the effect of the AXL inhibitor on immune cells in the tumor microenvironment was demonstrated in two tumor types with different characteristics." (PMID 35356198, 2022). "Several studies now suggest that AXL contributes to an immunosuppressive tumor microenvironment and can modulate the ability of immune cells to eliminate cancer cells." (PMID 35158733, 2022). "For the past few years, the receptor tyrosine kinase AXL has been considered as a promising target for tumor treatment." (PMID 36619616, 2022). "Accumulating evidence reveals a multifaceted role of AXL in promoting immunosuppression and resistance to anti-tumor immunity." (PMID 35572601, 2022).
tumor (continued). "Protein S (PROS1) is a recognized ligand of the Tyro3, AXL, and Mer (TAM) family of tyrosine kinases receptors, it was secreted by activated T cells or tumor-associated macrophages." (PMID 36685506, 2022). "In cancer, the TAM receptors, including AXL, promote macrophage polarization towards an immunosuppressive pro-tumor M2-like phenotype." (PMID 35572601, 2022). "Overexpression or hyperactivity of AXL is frequently observed in cancer in the context of tumor heterogeneity, plasticity, and the development of therapy-resistant persister cell populations." (PMID 35572601, 2022). "This review discusses recent advances in understanding AXL’s functions in different tumor compartments including cancer, vascular, and immune cells." (PMID 35158733, 2022). "To determine the optimal timing for administration of SKI-G-801, an AXL inhibitor, we investigated its anti-tumor effects based on inclusion at the immunochemotherapy and maintenance therapy stages." (PMID 35356198, 2022). "AXL is expressed and plays a role in different types of cells including tumor cells, fibroblasts, vascular cells and several immune cells." (PMID 35158733, 2022). "In the TC1 tumor model, M1 macrophages were significantly increased by AXL inhibition, with a sharp increase compared to the SoC protocol." (PMID 35356198, 2022). "AXL expression of ID8 tumor cells was also shown to inhibit the accumulation and activation of CD103+ cDCs in the tumor." (PMID 36011029, 2022). "AXL is a member of the TYRO3, AXL, and MERTK (TAM) family of receptor tyrosine kinases (RTKs) that can be activated by the ligand Gas6, which is closely associated with tumor progression." (PMID 36105100, 2022). "We next evaluated roles for MERTK, EGFR, and AXL in NSCLC tumor cell expansion, migration, and colony formation using siRNA-mediated knockdown." (PMID 35708914, 2022). "The growth arrest-specific protein 6 (GAS6)/AXL axis is upregulated in various tumor tissues, and it has been suggested to be another antiapoptotic pathway in addition to the BCL-2 family in some tumors." (PMID 36313732, 2022). "By testing multiple treatment strategies (such as add-on or alternative therapy) against the existing standard of care (SoC), we were able to confirm that AXL inhibitors induce changes in the tumor microenvironment (TME), in addition to tumor suppression." (PMID 35356198, 2022). "In VHL-deficient and hypoxic ccRCC tumor cells, protein kinase growth arrest-specific 6 (GAS6)/AXL is activated by HIF1A and HIF2A." (PMID 35659268, 2022). "RTKs that target MET, VEGFR-2 and AXL significantly increase the tumor suppressive effect and reduce the chance of tumor resistance to treatments." (PMID 36341335, 2022). "Normally, AXL has a low expression level during adulthood; however, its abnormal expression has been observed in various types of neoplasms including breast cancer." (PMID 36483567, 2022). "Taken together, these studies performed in numerous models have identified potential mechanisms of AXL-mediated immunosuppression, such as decreased tumor antigen presentation, suppression of pro-inflammatory cytokines, and disruption of immune infiltrates." (PMID 35572601, 2022). "Meanwhile, potential “on-target/off-tumour” effects of AXL-CAR T cells will be considered when they are further applied in clinic." (PMID 36261437, 2022). "Expression of MERTK and AXL on tumor-infiltrating macrophages polarizes them towards a pro-tumor M2-like phenotype." (PMID 34830794, 2021). "Inhibition of AXL by genetic or pharmacological means restored erlotinib sensitivity in these tumor models." (PMID 34071428, 2021). "More recent studies have further elucidated the prominent examples of EGFR, HER2, and AXL signaling contributing directly to tumor-driven immunosuppression." (PMID 33807608, 2021).